IL6 (interleukin 6)
Diseases named in the same sentence as IL6 in open-access papers (continued):
Sharing a sentence is not in itself a finding about the gene and the disease.
Sepsis (continued). "Silencing circDNMT3B can significantly increase the level of d‐lactic acid, FD‐40, MDA, diamine oxidase, IL‐10 and IL‐6, compared with sepsis group, while the SOD activity was lower." (PMID 32383354, 2020). "P2X7R pharmacological blockade with BBG decreased levels of inflammatory cytokines (i.e., IL-1β, IL-6, and IL-10), NO production, and neutrophil recruitment to the peritoneal cavity in a mouse model of sepsis." (PMID 33519492, 2020). "IL-6 also plays a major role in sepsis with IL-6 levels in serum correlating with onset and progression of the disease." (PMID 32967225, 2020). "Previous studies have indicated that IL-6, the most well-known traditional activator of STAT3, was a hallmark of many human chronic inflammatory states, including sepsis, rheumatoid arthritis (RA), and inflammatory bowel disease (IBD)." (PMID 32733162, 2020). "In further analyses, the diagnostic value of IL-6, sTREM-1, PCT, and CRP in the diagnosis of systemic inflammatory response syndrome and sepsis in feverish children was evaluated." (PMID 32655314, 2020). "Procalcitonin (PCT) and interleukin-6 (IL-6) have become popular biomarkers for predicting the prognosis of sepsis in the last decade." (PMID 32153412, 2020). "Neutrophils and monocytes from adults with sepsis have reduced activation and production of pro inflammatory cytokines (IL-1α, IL-6, TNF-α) in response to LPS." (PMID 31612119, 2019). "To do this, we cultivated recombinant IL-6 in phosphate-buffered saline (PBS) supplemented with patient's serum obtained from 3 different time-points (in sepsis, 1 and 3 months later) or with FBS." (PMID 31781117, 2019). "The present study aimed to investigate both the diagnostic and prognostic values of IL-6, PTX3, and PCT in the emergency department (ED) patients with sepsis and septic shock using the Sepsis-3 definitions." (PMID 31718563, 2019). "Furthermore, in dogs with naturally occurring systemic inflammatory response syndrome (SIRS) and sepsis, joint inflammation caused by idiopathic immune-mediated polyarthropathy, or with metaphyseal osteopathy (MO), an inflammatory bone disease, high plasma IL-6 concentrations were observed." (PMID 31344106, 2019). "Once the newer molecules of IL-6 inhibitors, which target only the trans-cellular pathway, become more established, as we gain experience in their use, complications of IL-6 inhibition such as sepsis can be minimized." (PMID 31523783, 2019). "During sepsis, the homeostasis between pro-inflammatory and anti-inflammatory cytokines is disrupted, resulting in the release of inflammatory factors, such as IL-6, IL-1β, and TNF-α." (PMID 31555126, 2019). "Higher pro-inflammatory IL-6 and anti-inflammatory IL-10 levels have been associated with DIC and development of MODS in sepsis." (PMID 31681719, 2019). "While IL-6 is considered to be an important inflammatory cytokine, its usefulness in diagnosing sepsis is still controversial." (PMID 31568522, 2019). "Interleukin-6 is a reliable marker for the early diagnosis and follow-up of sepsis (Gabay, Lamacchia & Palmer, 2010)." (PMID 31333903, 2019). "Dysregulated expression of the cytokines TNF-α and IL-6 has been found to correlate with sepsis mortality." (PMID 31420571, 2019). "Taken together, these results indicate that increase in proinflammatory ICAM1, VCAM1, and IL6 in HMECs during LPS induced sepsis in vitro is at least in part due to increase in expression of the lncRNAs HULC and UCA1." (PMID 31231228, 2019). "Sepsis induced a generalized up-regulation of both human and murine plasma cytokines (TNFα, IL-6, IL-10, IL-8/KC, MCP-1); it was additionally aggravated in P-DIE vs. P-SUR." (PMID 31297113, 2019). "Despite an increase of THBD in serum is associated with poorer outcome in sepsis, its circulating form as well as that of SDC1 reduces IL-6 expression, thereby serving to control an inflammatory response and preventing overwhelming immune reactions." (PMID 31396019, 2019).
Sepsis (continued). "In a prospective trial, sepsis patients with higher baseline interleukin-6 levels appeared more likely to respond to anti-tumor necrosis factor therapy." (PMID 31818332, 2019). "Liver injury occurs at early phase of severe sepsis, which is characterized by cholestasis, steatosis, hepatocellular injury, impaired regeneration, a decreased response to the cytokine interleukin-6, and high mortality." (PMID 31497584, 2019). "Blocking IL-6 with a monoclonal antibody in a primate model of sepsis, largely prevented LPS-induced coagulation activation once decreased significantly levels of prothrombin fragment 1+2 (F1+2) and thrombin-antithrombin complex." (PMID 31139194, 2019). "For example, in a study that measured the effectiveness of using IL-6 in predicting NS and included both 353 infants with sepsis and 691 normal infants, the results demonstrated that the sensitivity and specificity of IL-6 were 0.79 and 0.84, respectively." (PMID 31671729, 2019). "In contrast to our study, some have reported that PCT is superior to IL-6 for diagnosing severe sepsis and septic shock." (PMID 31718563, 2019). "IL-6 and PTX3 can be used as both diagnostic and prognostic biomarkers for sepsis and septic shock diagnosed in accordance with the Sepsis-3 definitions." (PMID 31718563, 2019). "In fact, lower mortality was observed in rats exposed to LPS and treated with a monoclonal antibody against TNF-α, and beneficiary effects were also observed for anti-IL-1β as well as anti-IL-6 antibody treatment in other experimental models of sepsis." (PMID 31075981, 2019). "In a large animal study with 120 mice, the effect of total IL-6 blockade or selective inhibition of IL-6 trans-signaling on survival of sepsis induced by cecal ligation puncture was compared." (PMID 31694340, 2019). "Yet, the levels of IL-6 and TNFα in serum are attenuated by alcohol in case of the sepsis group compared to the control sepsis group." (PMID 31739600, 2019). "Overall, IL-6 was superior to PTX3 and PCT in both diagnostic and prognostic value for sepsis and septic shock." (PMID 31718563, 2019). "Several cytokines also exhibited a significant sepsis × sex interaction [IL-6 (p = 0.009), IL-10 (p = 0.003), MIP-1α (p = 0.0149), KC (p = 0.003)]." (PMID 31278440, 2019). "Binary logistic regression analysis showed that plasma EPO, hepcidin, ferritin, IL-6, sTfR/log ferritin, RDW and SOFA score were associated significantly with 28-day mortality in patients with sepsis." (PMID 31183575, 2019). "The levels of PCT, IL-6, and sCD163 in the sepsis group were significantly higher than other two groups." (PMID 31915467, 2019). "IL-6 level was superior to PTX-3 and PCT levels in both diagnostic and prognostic value for sepsis and septic shock diagnosed in the emergency department using Sepsis-3 definitions." (PMID 31243609, 2019). "Evidence concerning the clinical value of IL-6 and PTX3 is controversial; however, prior studies have proposed PTX3 as a diagnostic and prognostic marker of sepsis." (PMID 31718563, 2019). "The diagnostic and prognostic value of IL-6 was superior to those of PTX3 and PCT for sepsis and septic shock." (PMID 31718563, 2019). "Among the traditional biomarkers, complete blood count (CBC), procalcitonin, and IL-6 are most commonly used in the diagnosis of sepsis." (PMID 31915467, 2019). "HBP played an essential role in the initial inflammatory reaction associated with sepsis-induced AKI, presumably by activating M1 macrophages and by suppressing TNF-α and IL-6 secretion." (PMID 31930151, 2019). "This was associated with lower levels of key inflammatory cytokines in the acute phase of sepsis including IL-6, TNF-alpha in response to CX43 blockade or deletion." (PMID 30735126, 2019). "We observed an increased unstimulated production of IL-6 and IL-1β in the time of sepsis, which further increased after LPS stimulation, demonstrating an unskewed ability to synthetize these cytokines." (PMID 31781117, 2019).
Sepsis (continued). "Most importantly, we identified a significant relationship between DNA methylation data and IL-10 and IL-6 cytokine levels, which are significantly increased in patients with sepsis, as well as with organ dysfunction." (PMID 31665078, 2019). "In dogs with inflammation experimentally induced by an injection of turpentine oil or canine sepsis models produced by administering infusions of either live Escherichia coli or lipopolysaccharide (LPS), induction of high levels of serum IL-6 are observed." (PMID 31344106, 2019). "LPS-injected Rag2 KO rats developed sepsis as indicated by increased TNFa, IL-6, IL-1b, and IL-10 levels and thrombocytopenia." (PMID 31921873, 2019). "The surge of proinflammatory cytokines in ACLF patients, such as TNF-α and interleukin 6 (IL-6), is comparable to those described in sepsis." (PMID 31317042, 2019). "The median values (IQR) of IL-6 in controls, sepsis, and septic shock were 0.6 (0.2-1.6), 89.9 (45.2-272.6), and 1378.6 (256.4-11062.1) pg/ml, respectively." (PMID 31243609, 2019). "In the present study, we evaluated the diagnostic and prognostic values of IL-6, PTX3, PCT, CRP, and lactate in patients with sepsis and septic shock diagnosed using Sepsis-3 definitions." (PMID 31718563, 2019). "Despite a subtle increase in Scr, serum IL-6 levels in sepsis-AKI models were 6–7 times higher than the levels in both I/R models." (PMID 30991873, 2019). "Of note, Il-6, the most common sepsis biomarker used in human neonates, was only at the late stage of sepsis (24 h p.i.)increased in newborn mice." (PMID 30976090, 2019). "IL-6 blockade therapy is beneficial to the prognosis of sepsis by blocking systemic inflammatory response." (PMID 30782124, 2019). "Increased cytokines, such as TNF-α and IL-6, are hallmarks of many human inflammatory states, including sepsis." (PMID 32082076, 2019). "Previously, DNA sensors exploiting EIS and DPV have been produced for the detection of sepsis biomarker interleukin-6 (IL-6), antibiotic resistance and fusion genes." (PMID 31817717, 2019). "As pointed out above, the proposed biomarkers CRP and IL-6 turn out to lack specificity for sepsis, which has long been considered as the prototypical systemic inflammatory condition." (PMID 30769887, 2019). "The 185 subgroup meta-analyses by ethnicity and age revealed three additive polymorphisms (TLR2 rs5743708 Arg753Gln, IL6 rs1800796-572G/C, and IL10 rs1800896-1082A/G) that were significantly associated with the risk of sepsis." (PMID 30683156, 2019). "In our experimental model, sepsis was characterized by hypotension and increase of IL-6, early marker of sepsis." (PMID 31333903, 2019). "The hyperinflammatory ARDS sub-phenotype is characterized by a higher prevalence of sepsis and severe shock, high plasma levels of inflammatory biomarkers (IL-6, IL-8, etc.), greater vasopressor use, and metabolic acidosis." (PMID 31842964, 2019). "We inferred that the relationship between AGP and CRP resides in the fact that they are secreted by the same cytokines, such as IL-1, IL-6, and glucocorticoids, to promote anti-inflammatory effects during early sepsis." (PMID 31309103, 2019). "These propolypeptides are released into the blood when inflammatory mediators activate endothelial cells, and they are known to positively correlate with the amounts of IL-6, IL-8, and IL-10 in sepsis patients." (PMID 31568522, 2019). "It serves as a biomarker of the sepsis, and elevated serum IL-6 level indicates the deterioration of the disease and higher tendency to death." (PMID 30782124, 2019). "IL-6 is an important player in the acute phase of inflammation and is closely related to the mortality of sepsis." (PMID 31787899, 2019). "Release of pro-inflammatory cytokines, particularly TNF-a, IL-6 is an important component of the host immune response and the role of these molecules in the pathogenesis of sepsis has been well studied." (PMID 30820191, 2019).
Sepsis (continued). "As expected, sepsis induced an acute increase in both inflammatory (TNFα, IL1β, IL-6) and anti-inflammatory (IL-10) plasma cytokine concentrations." (PMID 31248453, 2019). "Among 143 enrolled subjects (51 with sepsis, 46 with septic shock, and 46 healthy volunteers), serum levels of IL-6, PTX-3, and PCT were measured." (PMID 31243609, 2019). "Pro-inflammatory cytokines, such as interleukin (IL)-6, IL-1β, and tumor necrosis factor (TNF) α have been shown to contribute to sepsis-associated hepatocellular dysfunction." (PMID 30873161, 2019). "IL6 is a proinflammatory cytokine and serves as an important mediator during the acute phase response to inflammation in sepsis." (PMID 31682605, 2019). "In a model of sepsis involving lipopolysaccharide-activated macrophages, propofol was shown to inhibit the production of IL-6 by macrophages by 83%10." (PMID 30918320, 2019). "In one report on neonatal foals with naturally occurring sepsis, IL-6 levels were lower than healthy age-matched controls." (PMID 30931316, 2019). "Current clinical studies on post-surgery patients with severe sepsis show that IL-6 is markedly diminished in the first week of infection among survivors; however, among non-survivors, IL-6 increases during the first week of infection." (PMID 31671729, 2019). "A meta-analysis showed that IL-6 exhibited a combined sensitivity of 80% for sepsis and a specificity of 85%, and in the neonatal group, the combined sensitivity was 77.0% and specificity was 91.0%." (PMID 31671729, 2019). "MRSA-mediated induction of the sepsis-associated molecule C-reactive protein (CRP), the proinflammatory cytokines IL-6, IL-1β, and TNF-α were also attenuated by Epi-1 treatment." (PMID 31835381, 2019). "According to previous reports, the dysregulated expression of the cytokines, IL-6, TNF-α, and IL-1β, is associated with mortality in patients with sepsis." (PMID 31333903, 2019). "The plasma markers of inflammation, CRP and IL6, are known to be elevated during inflammation-mediated sepsis and lead to mortality." (PMID 31835381, 2019). "IL-6 is a pro-inflammatory cytokine which is involved in the inflammatory reaction at the early stage of sepsis." (PMID 30782124, 2019). "Several studies confirm a predictive value of IL-6 for mortality and organ dysfunction in sepsis or after major trauma." (PMID 31795299, 2019). "More importantly, the innate immune responses in Rag2 KO rats, such as high serum levels of TNFa, IL-1, IL-6, and IL-10, and the development of thrombocytopenia also represent those seen in patients with sepsis." (PMID 31921873, 2019). "We measured cytokine expression and production of IL-6, TNF-α and IFN-β in Ets2 knockdown or knockout macrophages and susceptibility to cecal ligation and puncture (CLP)-induced sepsis in Ets2-deficient mice." (PMID 31785145, 2019). "Increased interleukin (IL)-6 in patients with sepsis can induce an abruptly increased synthesis of hepcidin, causing decreased plasma iron." (PMID 31183575, 2019). "SDC-1, Ang-2, sTM, VAP-1 and IL-6 levels were measured at ICU admission from 619 patients with sepsis." (PMID 31512003, 2019). "Plasma levels of neutrophil extracellular trap components, lactoferrin and ILs, especially IL-6 and IL-8, are used to assess systemic immunity and inflammation, and thereby sepsis resistance." (PMID 31118098, 2019). "Our data showed that sepsis patients, when compared to healthy control subjects, had significantly increased blood levels of IL-6 (184.2 ± 25.8 vs. 6.2 ± 3.4 ng/mL, p < 0.001), a data that supports ongoing inflammation in the sepsis patients." (PMID 31791247, 2019). "During gram‐negative bacteria‐induced sepsis, lipopolysaccharide (LPS) drives the systemic production of inflammatory genes, such as interleukin (IL)‐1, IL‐6, IL‐8 and tumor necrosis factor‐alpha (TNF‐α), which all induce sepsis‐associated pathology." (PMID 30207412, 2019).
Sepsis (continued). "The optimal cut-off value to discriminate sepsis from controls was 52.60 pg/mL for IL-6 (sensitivity, 97.0%; specificity, 97.2%; P < 0.001) and 15.10 ng/mL for PTX3 (sensitivity, 92.6%; specificity, 97.4%; P < 0.001)." (PMID 31718563, 2019). "Another important cytokine during sepsis in humans and horses is IL-6, which is produced after cells are exposed to TNFα and IL-1β." (PMID 30931316, 2019). "Plasma concentration of CRP, PCT, and IL-6 decreased after 3 and 5 days of sepsis onset, thus indicating a gradual resolution of systemic inflammation." (PMID 31221993, 2019). "The purpose of the present study was to investigate both the diagnostic and prognostic value of IL-6, PTX-3, and PCT among patients with sepsis and septic shock diagnosed at an emergency department (ED) using the latest Sepsis-3 definitions." (PMID 31243609, 2019). "Cytokines, and in particular IL-6, rapidly increase during severe systemic inflammation, but its specificity for sepsis as a single biomarker, just like for CRP, turns out to be low." (PMID 30769887, 2019). "IL-6 serves as an important mediator during the acute phase of response to inflammation in sepsis, and its clinical value has been assessed in patients with various septic conditions in several studies." (PMID 31718563, 2019). "And its low expression was associated with advanced disease severity (APACHE II score and SOFA score) and systemic inflammation (CRP, PCT, TNF‐α, IL‐1β, IL‐6, and IL‐17) in sepsis patients." (PMID 31206807, 2019). "Certainly, there is a lot of progress to be made in the prediction models and better use of the early biomarkers of sepsis, such as IL-6 or pro-calcitonin." (PMID 30781454, 2019). "Further studies are warranted to elucidate the existence of the histamine-H1R-SOCS-1 axis in IL-6 homeostasis in autoimmune diseases and sepsis." (PMID 31780858, 2019). "Our study indicated that the serum cytokines such as TNF-α, IL-1β, and IL-6 were inhibited by hydrocortisone, which were consistent with previous studies in both animals and humans with sepsis." (PMID 31880211, 2019). "TAK-242 was developed as a small-molecule selective inhibitor of TLR4 signaling that suppresses the increase in serum cytokine levels TNF-a, IL-1, and IL-6 in murine and porcine models of sepsis, as well as in LPS challenged healthy volunteers." (PMID 30405628, 2018). "Our findings suggested that a reduction in the IL-6 level of ≥86% at 24 h from ICU admission is a survival predictor for patients with sepsis and septic shock in our population." (PMID 30400775, 2018). "Alterations in plasma levels of DcR3, PCT, CRP, and IL-6 were measured by ELISA and compared among patients with sepsis (n = 134), SIRS (n = 60) and normal adults (n = 50)." (PMID 29541387, 2018). "For example, it reduces serum TNF-α and IL-6 concentrations in patients and in preclinical models of sepsis, antagonizes LPS, regulates CD4+ T cell differentiation, and prevents/controls the disseminated intravascular coagulation (DIC) and infections." (PMID 30618740, 2018). "Here, for the first time, we demonstrate that AA is a novel small molecule inhibitor of the Notch signaling pathway and exerted anti-sepsis effects by preventing Notch3 from binding to the IL-6 promoter and regulating mitochondrial function." (PMID 29599924, 2018). "We chose to measure LDH, ALT, and IL-6, in particular because their serum levels are indicators of sepsis severity and mortality." (PMID 29434211, 2018). "This study showed that the effects of IL-6 were independent from the effects of TNF-α, IL-1β, and IL-12, but IL-6 was regulated by ILT4, which was associated with poor prognosis of sepsis." (PMID 29662678, 2018). "Ten hours after sepsis induction, expression of IL-6 and IL-1β as well as the neutrophil chemoattractants KC and MIP-2 in the lungs of neonatal mice were measured." (PMID 29720984, 2018).